EEF2K (eukaryotic elongation factor 2 kinase)
Diseases named in the same sentence as EEF2K in open-access papers (continued):
Sharing a sentence is not in itself a finding about the gene and the disease.
cancer (73 papers, 2010 to 2026). A tumor composed of atypical neoplastic, often pleomorphic cells that invade other tissues. "We explored the potential association between eEF2K gene alterations and clinical prognosis of patients with different types of cancer." (PMID 39592671, 2024). "Paradoxically, eEF2K deficiency led to more pronounced DNA damage and mitotic cell death in small intestinal stem cells and conversely, overexpression of eEF2K in cancer cells decreased radiation-induced apoptosis." (PMID 39003251, 2024). "In cancer, eEF-2K has been implicated in various cellular processes, including tumor cell proliferation, migration, and metastasis." (PMID 39861816, 2024). "Recent studies have revealed that eEF2K is associated with certain diseases including cancer and cardiovascular and neurodegenerative diseases." (PMID 34065377, 2021). "The promotion of cancer cell survival by eEF2K has been linked to nutrient management in rapidly proliferating solid tumours, where, due to the poor vascular structure, cancer cells have to adapt to prolonged nutrient deprivation." (PMID 32298235, 2020). "This is the converse of the type of effects seen in many cancer cells, where loss of eEF2K promotes cell death (generally under stressful conditions)." (PMID 29186827, 2017). "Recent studies have implicated eEF2K activity in other conditions that also highlight its potential as an important drug target, including in cancer." (PMID 25475470, 2014). "Additionally, the eukaryotic elongation factor 2 kinase (eEF2K), responsible for inhibitory eEF2 phosphorylation that impedes protein synthesis, is overexpressed in several cancers and associated with poor survival outcomes." (PMID 37747887, 2023). "The known ability of quercetin to induce oxidative stress and apoptosis in cancer cells likely complements the eEF2 K-siRNA, which silences a key survival pathway in TNBC cells." (PMID 40266550, 2026). "This outcome aligns with previous findings that eEF2 K inhibition, coupled with chemotherapeutic agents, can induce apoptosis in cancer cells." (PMID 40266550, 2026). "Recently, eEF2K has been targeted for cancer therapy, and siRNA-based gene therapy has emerged as an effective approach to silence overexpressed genes." (PMID 40266550, 2026). "We also explored the impact of exosomal communication between cancer cells and macrophages on eEF2K expression and the aggressiveness of cancer cells." (PMID 40624025, 2025). "The expression of eEF2K is usually upregulated to inhibit the translation elongation in nutrient limitation conditions in cancer for saving energy to enhance the cancer survival rate." (PMID 40567376, 2025). "Based on data from the literature, eEF2K promotes aggressive features of cancer cells through several mechanisms." (PMID 40624025, 2025). "eEF2K, an atypical Ca2+/calmodulin-dependent Ser/Thr kinase, is frequently overexpressed or hyperactivated in various cancer types and is, therefore, considered a compelling target for therapeutic intervention." (PMID 40807478, 2025). "eEF2K is an oncogenic kinase known for promoting cell proliferation, invasion, and migration in various cancers." (PMID 40725039, 2025). "The new compound C4 shows better ability to degrade eEF2K and stronger anti-cancer activity than C1." (PMID 39950798, 2025). "All of these highlight the prognostic significance of eEF2K and supporting its potential utility as a therapeutic target in various cancer types." (PMID 39592671, 2024). "We also utilized the Human Protein Atlas (HPA) to confirm eEF2K RNA and protein expression in various cancer tissues." (PMID 39592671, 2024).
cancer (continued). "The expression of eEF2K promotes cancer cell survival, and the level of this protein is increased in many cancer cells to adapt them to microenvironmental conditions, including hypoxia, nutrient depletion, and acidosis." (PMID 39061201, 2024). "Further, utilizing the data in the CPTAC-TCGA datasets containing 364 TCGA cancer samples, we also detected eEF2K and eEF2 protein phosphorylation site in different cancer types and analyzed the changes of eEF2K and eEF2 protein phosphorylation levels." (PMID 39592671, 2024). "Scientific evidence shows that eEF2K regulates the cell cycle, autophagy, apoptosis, angiogenesis, invasion and metastasis in various types of cancer." (PMID 39061201, 2024). "Next we tested the correlation between eEF2K protein expression and functional change in human cancer." (PMID 39592671, 2024). "Our findings suggest that eEF2K has dual roles in cancer progression, with its expression correlating with patient prognosis." (PMID 39592671, 2024). "Previous studies have shown the potential therapeutic utility of eEF2K in sensitizing cancer cells to paclitaxel." (PMID 38084501, 2024). "Previous studies have shown that the physiological roles of eEF2K vary significantly across different cancer types, suggesting a context-dependent function." (PMID 39592671, 2024). "To detect the eEF2K gene expression status in various cancers, we comprehensively screened 7,452 primary tumors and 1,196 normal adjacent-tissue samples spanning 33 cancer or carcinoma types in the TCGA database in the study using the TIMER2 tool." (PMID 39592671, 2024). "Although eEF-2K has been studied extensively in cancer and some other diseases, its role in immune responses, particularly in T cells, remains underexplored." (PMID 39861816, 2024). "It was observed that in breast cancer carcinoma cells, the lead PROTAC reduced total eEF2K protein levels and phosphorylation of eEF2, and importantly apoptosis was observed in this cancer model when treated with PROTAC." (PMID 36770760, 2023). "The role of eEF2K is incredibly diverse and has been scrutinized in several different diseases including cancer and neurological disorders—with numerous studies inhibiting eEF2K as a potential treatment option, as described in this paper." (PMID 36770760, 2023). "eEF2K has been deemed to be of importance as a target in cancer solid tumors, cardiovascular conditions, neurodegenerative diseases (including depression), and both hypoxic and nutritional stress." (PMID 36770760, 2023). "We next sought to investigate the relationship between eEF2K activity and synergy to PI3Ki and MEKi treatment in a larger panel of cancer models." (PMID 35513296, 2022). "This study suggests that targeting EEF2K to control mRNA translation can be used as a unique approach to inhibit cancer by controlling cholesterol metabolism." (PMID 35408842, 2022). "Knockdown of eEF-2K caused significant inhibition of the migratory and invasive potential of MDA-MB-436 and MDA-MB-231 cancer cells." (PMID 35682990, 2022). "Negative regulation of translation elongation at the eEF2 step by eEF2 kinase (eEF2K) is countered by mTORC1-mediated phosphorylation of eEF2K in cancer cells." (PMID 36187485, 2022). "In summary, this study demonstrates that eEF2K enhances PD-L1 stability and expression via GSK3β inactivation, leading to cancer cells escape from immune surveillance." (PMID 35347072, 2022). "Together, our study uncovers eEF2K activity as a key mediator of responses to PI3Ki plus MEKi and as a potential biomarker to predict synergy to cotreatment in cancer cells." (PMID 35513296, 2022). "In summary, we found that the activity of eEF2K helps rationalizing the extent by which PI3Ki + MEKi cotreatment synergize in reducing cancer cell survival and proliferation." (PMID 35513296, 2022). "This is the first report to suggest that targeting EEF2K can be used to modulate cholesterol metabolism to treat cancer." (PMID 35408842, 2022).
cancer (continued). "Eukaryotic elongation factor 2 kinase (eEF2K) is a highly conserved α kinase and is increasingly considered as an attractive therapeutic target for cancer as well as other diseases." (PMID 35956836, 2022). "In recent years, along with the increased potential of eEF2K as a drug target in cancer, as well as in cardiovascular and neurodegenerative diseases, a growing attention has been paid to the development of eEF2K inhibitors." (PMID 35956836, 2022). "Taken together, studies highlight the importance of eEF2K in both cancer cells and microenvironmental cells." (PMID 35010954, 2021). "Although important progress has been made in the research and development of eEF2K inhibitors, the complete mechanism of anti-cancer drugs is usually more complicated than single-target action." (PMID 33673713, 2021). "eEF2K was proposed to be responsible for cell survival under acidic and hypoxic conditions in cancer cells and fibroblasts." (PMID 35010954, 2021). "The suppression of this mechanism would enable eEF2K to be used mechanistically as a new drug target for single or multi-agent cancer chemotherapeutics." (PMID 33673713, 2021). "eEF2K plays a role in cancer cell survival (decreasing protein synthesis and energy/amino acids consumption during nutrient depletion) and migration, angiogenesis, and the synthesis of integrins and other proteins." (PMID 34830196, 2021). "eEF2K inhibitors for cancer therapeutics take advantage of the molecule’s signaling and regulatory pathways." (PMID 34532346, 2021). "Activation of eEF2K by oxidized low-density lipoprotein inhibits apoptosis in macrophages and promotes survival of cancer cells." (PMID 35010954, 2021). "Despite its prevalence in cancer development, eEF2K is also vital in the immune response during infection as it plays a critical role in the metabolic regulation of different immune cells." (PMID 34532346, 2021). "Special attention is given to those inhibitors that have been already validated in vivo, with the overall aim to provide reference context for the further development of new first-in-class anti-cancer drugs that target eEF2K." (PMID 33673713, 2021). "Since eEF2K has a regulatory effect on multiple links in the cell cycle process, this represents an attractive new target for future cancer treatments." (PMID 33673713, 2021). "eEF2K is highly expressed and regulates apoptosis, cell survival, autophagy in multiple cancer cells." (PMID 34532346, 2021). "Downregulation of expression or silencing of eEF2K has been demonstrated the inhibition of proliferation, migration, and invasion in many cancer cell lines." (PMID 34776832, 2021). "The physiological role eEF2K plays in developing and progressing several diseases, especially cancers, has led researchers to design therapeutics that target the protein kinase." (PMID 34532346, 2021). "This suggests the dual role of eEF2K in multiple cancer cell lines, and future investigation is required." (PMID 34532346, 2021). "The expression of eEF2K promotes survival of cancer cells, and the level of this protein is increased in many cancer cells to adapt them to the microenvironment conditions including hypoxia, nutrient depletion, and acidosis." (PMID 33673713, 2021). "Drug combination therapies with eEF2K inhibitors have been used to reduce doses of single drug resistance and increase the efficacy of cancer therapies." (PMID 34532346, 2021). "Through the lens of cancer therapeutics, eEF2K is a valid and prominent target, as primary research on focused on the protein kinase’s role in cancer." (PMID 34532346, 2021). "The physiological function of eEF2K and its role in the development and progression of cancer are here reviewed in detail." (PMID 33673713, 2021). "These early data indicate the importance of eEF2K in cancers, and suggest that it is a potential new target for cancer chemotherapeutic treatments." (PMID 33673713, 2021).
cancer (continued). "This leads to a pivotal role in drug development, and eEF2K is mainly being explored as a therapeutic target for numerous diseases, including cancers, neurodegenerative diseases, and cardiovascular diseases." (PMID 34532346, 2021). "Mounting evidence shows that eEF2K regulates the cell cycle, autophagy, apoptosis, angiogenesis, invasion, and metastasis in several types of cancers." (PMID 33673713, 2021). "Rapamycin combined with mitoxantrone exhibited enhanced inhibitory effects on cancer cells by depressing eEF-2K–driven increase in Akt signaling and cytoprotective autophagy." (PMID 33144562, 2020). "When cancer cells are exposed to rapamycin, there is a robust elevation of p-eEF2 at Thr 56, indicating the activation of eEF-2K." (PMID 33144562, 2020). "A recent study that focused on the migratory and metastatic potential of cancer cells showed that knockdown or chemical inhibition of eEF2K led to reduced integrin expression and decreased migration and invasion both in vitro and in vivo." (PMID 32298235, 2020). "eEF2K is also required to maintain energy production during acidosis and hypoxia, when it significantly reduces ATP levels and induces cancer cell death." (PMID 32298235, 2020). "Of particular importance is its role in regulating autophagy, a growing data including our own support the notion that eEF-2K-mediated autophagy aids the growth of cancer cells in vitro and in vivo in response to metabolic or therapeutic stresses." (PMID 33144562, 2020). "Our study discloses the diverse role of eEF2K in cell biology and complexity of eEF2K in cancer development, which lays foundation for the development of new anticancer therapeutic strategies." (PMID 32054489, 2020). "In conclusion, we report that eEF-2K contributes to the activation of resistance signaling pathways of mTOR inhibitor, suggesting a novel strategy to enhance mTOR-targeted cancer therapy through combining mitoxantrone, an eEF-2K inhibitor." (PMID 33144562, 2020). "To investigate the role of eEF2K in cancer cell proliferation, we depleted or overexpressed eEF2K in A549 non-small lung cancer cells." (PMID 32054489, 2020). "eEF2K is an evolutionarily-conserved mediator of cellular responses to nutrient deprivation and is expressed at high levels in certain cancers." (PMID 32054489, 2020). "As a negative regulator of protein synthesis, eukaryotic elongation factor-2 kinase (eEF-2K) exerts a critical role in the regulation of autophagy and apoptosis in cancer cells." (PMID 31616642, 2019). "We found that both TSC22D3 and EEF2K exhibited biphasic dose- and time-dependent expression following cancer exosomes transfection." (PMID 30008265, 2018). "eEF2K plays a key role in the response to DNA damaging stress and has been reported to regulate the sensitivity of cancer cells to several therapeutic drugs, including 2-DG, velcade, curcumin, TRAIL and temozolomide." (PMID 29050305, 2017). "eEF2K regulates many cellular processes, such as protein synthesis, cell cycle progression, autophagy and apoptosis in cancer cells." (PMID 29050305, 2017). "eEF2K is overexpressed in different types of cancer, including HCC, and the expression correlates with poor patient survival." (PMID 29050305, 2017). "Several studies have shown that eEF2K helps to promote the survival of cancer cells in vitro, especially under nutrient-deprived conditions (reviewed) or during acidosis." (PMID 29186827, 2017). "Such a dual role of eEF2K in cancer would be analogous to the situation for other pathways involved in cell metabolism, such as autophagy and mTORC1." (PMID 29186827, 2017). "Eukaryotic elongation factor 2 kinase (eEF2K), an emerging molecular target for cancer therapy, contributes to cancer proliferation, cell survival, tumorigenesis, and invasion, disease progression and drug resistance." (PMID 26918606, 2016).
cancer (continued). "Here we show that inhibiting eEF2K or knocking down its expression renders cancer cells sensitive to death under nutrient-starved conditions, and that this is rescued by compounds that block protein synthesis." (PMID 26795954, 2016). "As noted, recent data show that eEF2K is important for the ability of cancer cells to withstand nutrient deprivation, and promotes breast cancer." (PMID 26795954, 2016). "We conclude that eEF2K protects cancer cells against nutrient starvation by inhibiting protein synthesis rather than by activating autophagy." (PMID 26795954, 2016). "The emerging data which show that eEF2K protects cancer cells against nutrient deprivation prompted us to examine how it exerts these cytoprotective effects." (PMID 26795954, 2016). "We investigated the potential of targeting eEF-2K by rottlerin, a Kmala Tree-derived compound with anti-cancer activity." (PMID 25215932, 2014). "We also found that the transfection of miR-21-3p resulted in a >50% decrease in the mRNA expression of EEF2K, which is a valid target for anti-cancer treatment." (PMID 24098708, 2013). "In recent years eukaryotic elongation factor 2 kinase (eEF-2K) has garnered interest as a potential cancer-therapeutic target." (PMID 22911754, 2012). "It has been suggested that eEF-2K mediates cytoprotection to some anti-cancer therapies through the up-regulation of autophagy." (PMID 22911754, 2012). "It has been suggested that inhibiting eEF-2K blunts the ability of transformed cancer cells to up-regulate autophagy, a cellular stress response." (PMID 22911754, 2012). "Moreover, eEF2K expression is associated with shorter survival in PDAC patients and other cancers, highlighting its significance as a biomarker for poor prognosis." (PMID 40624025, 2025). "eEF2K has been shown to facilitate cancer cell survival under these conditions." (PMID 40624025, 2025). "Additionally, eEF2K induces autophagy to provide alternative energy sources for maintaining cancer cell proliferation and survival." (PMID 40624025, 2025). "Dysregulated eEF2K expression is implicated in the pathogenesis of many human cancers, including triple‐negative breast cancer (TNBC), making it a plausible therapeutic target." (PMID 38084501, 2024). "In the present study, we performed a pan-cancer analysis of eEF2K using the TCGA and GEO databases, exploring its potential molecular mechanisms in terms of gene expression, total protein and protein phosphorylation, survival status, genetic alterations, and related pathways of action." (PMID 39592671, 2024). "In addition to the regulatory role of eEF2K, our analysis revealed significant alterations in the total protein expression and phosphorylation of eEF2 across several cancer types." (PMID 39592671, 2024). "Increasing evidence supports eEF2K as a promising therapeutic target for cancer including TNBC." (PMID 38084501, 2024). "C1 therefore might serve as a great candidate agent for further exploring eEF2K function in both physiological and pathological processes and provide a therapeutic avenue for treating cancers that are dependent on eEF2K." (PMID 38084501, 2024). "Furthermore, eEF2K is widely used as a target protein in cancer research, so our study represents a novel application of an old target, breaking through the limitations of scientific research." (PMID 39180059, 2024). "The KEGG data suggests that the role of eEF2K in cancer pathogenesis may be related to the GnRH, neurotrophin, insulin, and MAPK signaling pathways." (PMID 39592671, 2024). "Moreover, eEF2K promotes the survival of cancer cells and primary neurons under hypoxia through a similar mechanism." (PMID 39003251, 2024).